IL17RB (interleukin 17 receptor B)
Diseases named in the same sentence as IL17RB in open-access papers (continued):
Sharing a sentence is not in itself a finding about the gene and the disease.
gastric cancer (continued). "Together, the results suggest that IL-17B/IL-17RB signal may induce stemness in gastric cancer cells by activating the AKT/β-catenin pathway." (PMID 27146881, 2016). "We postulate that amplified IL-17RB in gastric cancer tissues may depend on IL-17B derived from the tumor microenvironment." (PMID 27146881, 2016). "Furthermore, exogenous rIL-17B significantly promoted the stemness of gastric cancer cells depending on IL-17RB and induced the expression of IL-17RB." (PMID 27146881, 2016). "To investigate whether IL-17RB expression affected the survival of gastric cancer patients, we performed immunohistochemistry (IHC) to analyze IL-17RB expression in 239 gastric cancer specimens by using a tissue microarray." (PMID 27146881, 2016). "We found that IL-17RB expression was significantly upregulated in spheroid cells and Lgr5-positive cells from the same tumor tissues of patients with gastric cancer (GC), which was closely correlated with the degree of cancer cell differentiation." (PMID 33649532, 2021). "Our previous results also indicated that the IL-17B/IL-17RB signal can activate the AKT/β-catenin pathway in gastric cancer.To elucidate how IL-17B promotes MSCs stemness, proliferation and migration, we analyzed the expression of proteins that could be activated by IL-17 family cytokines." (PMID 28145881, 2017). "Our data also showed that there was a positive correlation between IL-17RB and Oct4, Nanog, Lgr5, or Sall4 mRNA expression, and that the expression of Oct4, Sox2, and Sall4 proteins increased in proportion to the increased expression of IL-17RB in gastric cancer tissues." (PMID 27146881, 2016). "To clarify whether there was a relationship between the expression of IL-17RB and stemness in gastric cancer tissues, we first detected the expression of Oct4, Nanog, Lgr5, and Sall4 mRNA using real-time quantitative PCR, and analyzed the relationship between them and IL-17RB mRNA." (PMID 27146881, 2016). "However, the role of IL-17B/IL-17RB (IL-17 receptor B) signaling to stemness of gastric cancer remains unknown." (PMID 27146881, 2016). "Therefore, IL-17RB may be a significant marker in therapy for gastric cancer patients." (PMID 37686343, 2023). "The relevance of these in vitro results to human gastric cancer is supported by the positive correlation between IL-17RB and OCT4, NANOG, LGR5, and SALL4 mRNA expression in human gastric cancer tissues." (PMID 32373132, 2020). "IL-17B/IL-17RB signaling promoted the upregulation of stemness and EMT formation in gastric cancer cells treated with exogenous recombinant human IL-17B (rIL-17B) by the AKT/β-catenin pathway." (PMID 27146881, 2016). "However, the role and mechanism of IL-17RB in gastric cancer is unknown." (PMID 27146881, 2016). "To understand the relationship of RORα and ILC2s-related markers and signature cytokines in patients with gastric cancer, we analyzed the correlation between RORα and T1/ST2, IL-17RB, CRTH2, ICOS, CD45, IL-13, and IL-5 in mRNA levels." (PMID 24741632, 2014). "Because the ligands of IL-17RB were IL-17B and IL-17E/IL-25, we quantitated the expressions of IL-17B and IL-17E mRNA in gastric cancer tissues and matched non-cancerous tissues by real-time quantitative PCR." (PMID 27146881, 2016). "Gastric cancer tissues with IL-17RB mRNA levels higher than paired non-cancerous tissues were defined as the high group, relative to a low group." (PMID 27146881, 2016). "In order to explore the role of IL-17RB in gastric cancer, we evaluated the expression of IL-17RB protein in paired non-cancerous and gastric cancer tissues by western blot analysis." (PMID 27146881, 2016). "To elucidate how IL-17B/IL-17RB signaling promotes gastric cancer stemness and EMT, we analyzed the expression of proteins that could bind to the SEFIR domain within the cytoplasmic tails of IL-17RB." (PMID 27146881, 2016).
gastric cancer (continued). "Our data showed that the mRNA expression levels of the transcription factors RORα and GATA3, the receptors T1/ST2 and IL-17RB, surface markers CRTH2, and type 2 cytokines IL-33, IL-5, and IL-4 were significantly increased in PBMCs from patients with gastric cancer compared to healthy controls." (PMID 24741632, 2014). "Together, our results indicate that the IL-17B/IL-17RB signal can promote the growth and migration of tumor cells, and upregulate cell stemness through activating the AKT/β-catenin pathway in gastric cancer, suggesting that IL-17RB may be a novel target in human gastric cancer therapy." (PMID 27146881, 2016).
breast tumor (7 papers, 2014 to 2021). "IL-17RB is also overexpressed in a subset of breast tumors and is associated with poor prognosis." (PMID 25340344, 2014). "IL-17RB is overexpressed in a subset of breast tumors and is associated with poor prognosis." (PMID 25340344, 2014). "Similary, the IL17B/IL17RB pathway promotes resistance to paclitaxel in breast tumors via the ERK1/2 pathway." (PMID 34724890, 2021). "In vivo, IL-17B induced resistance to paclitaxel and treatment with an anti-IL-17RB neutralizing antibody completely restored breast tumor chemosensitivity, leading to tumor shrinkage." (PMID 29371916, 2017). "On the contrary, analysis on a fresh breast tumor biopsy, by flow cytometry, revealed that IL-17RB was expressed by the EpCAM+ Cytokeratin+ tumor cells and by some fibroblasts, but also immune subpopulations within the tumor microenvironment." (PMID 29371916, 2017). "In line with the clinic data, the expression of IL-17RB is also variable among different breast tumor cell lines." (PMID 27909985, 2017). "Further investigation showed that cancer cells in the TDLNs enhanced their malignancy by up‐regulating oncogenic receptor, IL‐17rb, in both syngeneic mouse breast tumor model and clinical patients." (PMID 28993429, 2017). "Although they share the IL-17RB chain as co receptor, pro-oncogenic features were described for the breast tumor cell secreted IL-17B, whereas tumor suppressor role was associated to the normal breast epithelial cells secreted IL-17E." (PMID 26154409, 2015). "We next investigated whether activation of the IL-17B/IL-17RB pathway was involved in the development of resistance to conventional chemotherapeutic agents, such as paclitaxel, in breast tumors." (PMID 29371916, 2017).
colorectal cancer (7 papers, 2019 to 2025). A primary or metastatic malignant neoplasm that affects the colon or rectum. "The P4HAs stabilize and promotes collagen I expression, and IL17RB promotes downstream c‐Jun activation, which together contribute to colorectal cancer (CRC) metastasis." (PMID 39764560, 2025). "In this respect, the long term targeting on IL17RB to monitor tuft cell-like human colorectal cancer still needs further research to avoid the potential damage to the homeostasis of colorectal mucosa." (PMID 32733896, 2020). "The expression of IL17RB was then proven to be a potential marker for the lineage tracing of human colorectal cancer stem cells." (PMID 32733896, 2020).
allergic asthma (4 papers, 2016 to 2022). A asthma with a basis in a pathological type I hypersensitivity reaction. "Data support methylated IL17RB mRNA possibly becoming a new therapeutic target for chronic allergic asthma." (PMID 36250525, 2022). "IL25 also triggers expression of type 2 cytokines, activates type 2 innate lymphoid cells (ILC2 cells) and induces allergic asthma, all of which is dependent on its receptor, IL17RB." (PMID 36685501, 2022). "IL-17E (also known as IL-25) is a key regulator of type 2 immune responses and driver of inflammatory diseases, such as allergic asthma, and requires both IL-17 receptor A (IL-17RA) and IL-17RB to elicit functional responses." (PMID 35863378, 2022). "Here we conduct a gene-based analysis of variants in type 2 cytokine related genes (i.e. IL4, 5, 13, 25, 33 and 37, IL17RB, CRLF2 and TSLP) as risk factors for allergic asthma at school age and study their interaction with specific viral infections in early childhood." (PMID 36685501, 2022). "Thus, the m6A methylation of IL17RB mRNA, regulated by demethylase ALKBH5, may play an important role in the pathogenesis of allergic asthma, and might be a new therapeutic target." (PMID 36250525, 2022).
allergic rhinitis (4 papers, 2011 to 2023). Inflammation of the nasal mucous membranes caused by an IgE-mediated response to external allergens. "In the case of allergic rhinitis, the expression of IL17RB on CD4 T cells also increased in the blood of patients with seasonal allergic rhinitis after exposure to natural allergens." (PMID 36591273, 2022). "Myeloid dendritic cells (DCs) in patients with allergic rhinitis (AR) express higher levels of IL-17RB, ST2, and TSLPR." (PMID 32309281, 2020). "Wang H and colleagues reported in their 2010 study that allergen exposure to peripheral blood mononuclear cells, derived from patients suffering from seasonal Allergic Rhinitis (AR), augmented the expression of IL-17RB, a key modulator of basophil apoptosis and degranulation." (PMID 37430199, 2023). "Comparable to our findings, IL17RB has recently been shown to be the most differentially expressed gene in allergen challenged peripheral blood mononuclear cells from patients seasonal allergic rhinitis compared to healthy controls." (PMID 21473777, 2011).
colitis (4 papers, 2012 to 2023). Inflammation of the colon. "Previous study shows that IL17B can compete with IL25 for binding IL17RB to inhibit the pathologic role of IL25 in colitis." (PMID 36814913, 2023). "Although the percentage of IL-17Rb-expressing Treg cells was slightly elevated in mice treated with dextran sulfate sodium (DSS) water to induce colitis (DSS-induced colitis), the rate was only approximately 2%." (PMID 36717741, 2023).
thyroid cancer (4 papers, 2018 to 2020). "IL-17RB is upregulated in thyroid cancer tissues compared with normal thyroid tissues." (PMID 32373132, 2020). "Indeed, in the SW1736 thyroid cancer cell line, IL-17B-dependent stimulation of IL-17RB induces ERK1/2 activation and increases expression of the matrix metalloproteinase MMP-9 expression, a key mediator of tumor invasion and metastasis formation." (PMID 32373132, 2020).
dermatitis (3 papers, 2019 to 2023). An inflammatory process affecting the skin. "MEG3 is co-expressed with anti-inflammatory genes that are downregulated by IL17C and IL17RB, and it is negatively correlated with genes that when knocked out in mice, it induces chronic inflammation and dermatitis." (PMID 36869839, 2023).
leukemia (3 papers, 2016 to 2025). A malignant (clonal) hematologic disorder, involving hematopoietic stem cells and characterized by the presence of primitive or atypical myeloid or lymphoid cells in the bone marrow and the blood. "Previous studies have shown an oncogenic role for IL-17RB in murine leukemia cells." (PMID 27146881, 2016). "Interestingly, IL-17RB knockdown in MOLM-13 AML cells had a stronger effect than IL-17B knockdown in vivo, reflecting the potential contribution of the microenvironment-derived IL-17B to the signal delivered to IL-17RB-positive leukemia cells." (PMID 32373132, 2020).
nasal polyps (3 papers, 2016 to 2025). "Other studies showed that in patients with CRSwNP, the tissues of nasal polyps accumulate more dendritic cells (DC), expressing IL-17Rb, ST2, and TSLPR on their surface, than the tissues of healthy individuals." (PMID 40358177, 2025). "This study aimed to measure the expressions of IL-17RB, ST2 and TSLPR, receptor of IL-25, IL-33, and TSLP respectively, on myeloid DCs in nasal polyps (NP) and evaluate their association with local Th2 inflammation and disease severity in patients with NP." (PMID 30519393, 2018). "In conclusion, we identify functional IL-17RB as a marker of local TH2 cells present in chronically inflamed nasal polyp tissue from patients with CRSwNP." (PMID 26684290, 2016). "We next examined whether IL-17RB expression colocalized with TH2 cytokines in nasal polyp explant T-cell cultures." (PMID 26684290, 2016). "Clonality was examined by T-cell receptor variable β-chain (TCR Vβ) analysis with the immunoSEQ assay and compared in IL-17RB+CD4+ and IL-17RB−CD4+ cells sorted from nasal polyp explant cultures of 4 patients with CRSwNP." (PMID 26684290, 2016). "IL-25 receptor (IL-17RB)–expressing TH2 effector cells were identified in nasal polyp tissue but not the healthy nasal mucosa or periphery." (PMID 26684290, 2016).
Obesity (3 papers, 2020 to 2025). Accumulation of substantial excess body fat. "We found IL11RA and IL17RB were downregulated, IL19 and IL25 were upregulated in obesity group compared with normal group." (PMID 33197880, 2020).
prostate carcinoma (3 papers, 2016 to 2024). A carcinoma that arises from epithelial cells of the prostate gland. "IL-17RB expression is higher in cancer-associated fibroblasts from prostate cancer patients than in fibroblasts from benign prostate hyperplasia." (PMID 32373132, 2020). "Our former research results show that IL-17A and IL-17 F contribute to the pathogenesis of benign prostatic hyperplasia (BPH) and prostate cancer (Pca) while IL-17E interacting with IL-17RB might have an anti-tumor effect." (PMID 27716046, 2016).
pulmonary fibrosis (3 papers, 2019 to 2022). Chronic progressive interstitial lung disorder characterized by the replacement of the lung tissue by connective tissue, leading to progressive dyspnea, respiratory failure, or right heart failure. "Recently, it was reported that IL-17B, which (like IL-25) is a ligand for IL-17RB, is crucial for development of bleomycin-induced pulmonary fibrosis in mice by promoting type 3 immune responses in mice." (PMID 31745167, 2019).
acute myeloid leukemia (2 papers, 2020 to 2025). Acute myeloid leukemia (AML) is a group of neoplasms arising from precursor cells committed to the myeloid cell-line differentiation. "Additionally, mRNA expression profiles analysis in the HemaExplorer database showed that IL-17B and IL-17RB are strongly expressed in acute myeloid leukemia (AML), compared with normal hematopoietic stem cells." (PMID 32373132, 2020).
autoimmune disease (2 papers, 2022 to 2024). A disorder resulting from loss of function or tissue destruction of an organ or multiple organs, arising from humoral or cellular immune responses of the individual to their own tissue constituents. "IL-17RB, IL-23a, IL-21, and IL-6 are significantly related to autoimmune diseases." (PMID 35358276, 2022).
bladder cancer (2 papers, 2016 to 2023). "We compared expression and location of IL-17 cytokine family IL-17A, IL-17E and IL-17 F and their receptors IL-17RA, IL-17RB and IL-17RC in tissues derived from subjects with cystitis, bladder polyp and bladder cancer in parallel." (PMID 27716046, 2016). "Global IL-17RB immunoreactivity was significantly higher in the tissue sections from cystitis than that from bladder cancer (p = 0.025)." (PMID 27716046, 2016). "Such reduction in bladder cancer is possibly because the damaged or abnormal structural cells and malignant cells express less IL-17E and its receptor IL-17RB." (PMID 27716046, 2016). "On the other hand, it is interesting that reduced expression of IL-17E and IL-17RB in bladder cancer." (PMID 27716046, 2016). "The results of a complex study on the immunoreactivity of the ligands and receptors of the IL-17 family in patients with bladder cancer showed significantly elevated IL-17A, IL-17F, and IL-17RC immunoreactivity in the bladder cancer group but decreased IL-17E, IL-17RA, and IL-17RB immunoreactivity." (PMID 37371647, 2023). "Our data here showed that IL-17E and IL-17RB expression was elevated in cystitis but reduced in bladder cancer, possibly indicating that IL-17E might also be involved in the pathogenesis of benign urinary diseases." (PMID 27716046, 2016). "Compared with subjects with cystitis, immunoreactivity for IL-17A, IL-17 F and IL-17RC was significantly elevated in the group of bladder cancer (p < 0.01), while immunoreactivity of IL-17E, IL-17RA and IL-17RB, and the infiltrating neutrophils were decreased (p < 0.05)." (PMID 27716046, 2016).
helminth infection (2 papers, 2021 to 2025). "Supraoptimal ILC2 stimulation by IL-25 resulting from tuft cell Il17rb deficiency or prolonged succinate exposure induces a state of hypoproliferation in ILC2s, also observed in chronic helminth infection." (PMID 40074948, 2025). "Similar to the tissue sampled post-helminth infection, probes to IL17RB, TAS2R16 and DCLK-2 co-localized with POU2F3 probe, but in a lower number of cells, as expected from our IHC data." (PMID 34880874, 2021). "Our findings unequivocally demonstrate an intrinsic requirement for IL-17RB in ILC2s to foster proliferation and induce IL-13 expression upon succinate-mediated circuit stimulation, as well as to mount effective responses to clear helminth infections." (PMID 40074948, 2025).
intestinal cancer (2 papers, 2023 to 2025). "Recent studies linking IL-25 and IL-17RB to intestinal cancer warrant further characterization of this cytokine axis." (PMID 40074948, 2025).
polyp (2 papers, 2016). A usually exophytic mass attached to the underlying tissue by a broad base or a thin stalk. "We also observed that there were more neutrophils in cystitis tissue than polyp and cancer, accompanied with increased IL-17RA, IL-17E and IL-17RB expression." (PMID 27716046, 2016). "TH2 cytokine expression was determined by means of flow cytometry in polyp explants cultured in the presence of recombinant human IL-25 or IL-33 to evaluate whether IL-17RB and ST2 expressed on polyp T cells were functional." (PMID 26684290, 2016).
adult T-cell leukemia (1 paper, 2018). "In HTLV-positive adult T-cell leukemia IL17RB is overexpressed as well indicating an oncogenic function in this disease." (PMID 30680064, 2018).
aortitis (1 paper, 2019). Inflammation of the aorta. "Further study is needed to elucidate the contribution of IL-17RB+ γδ T cells in local lesions to development of aortitis in Il1rn−/− mice." (PMID 31745167, 2019). "On the other hand, in the local lesions of aortitis in Il1rn−/− mice, we identified CD11c+ DCs, Mac2+ macrophages, γδ T cells and B cells as IL-25 receptor (IL-17RB)–expressing cells." (PMID 31745167, 2019).
atherosclerosis (1 paper, 2019). A disease characterized by the build-up of fatty material and calcium deposition in the arterial wall resulting in partial or complete occlusion of the arterial lumen. "In the present study we attempted to investigate the direct effect of the IL25-induced splenic ILC2 (Lin−CD45+IL17RB+ICOS+IL7raint) population on the development of atherosclerosis by its adoptive transfer to hypercholesterolaemic apoE−/− mice." (PMID 31823769, 2019). "In the present study we attempt to further characterize the splenic IL25-induced ILC2 subset (Lin−CD45+IL17RB+ICOS+IL7raintermediate) as well as investigate the cells subset’s direct effect on atherosclerosis development through its adoptive transfer to atherosclerosis-prone apoE−/− mice." (PMID 31823769, 2019). "The aim of the current study is to characterize the interleukin 25 (IL25)-induced splenic ILC2 population (Lin−CD45+IL17RB+ICOS+IL7raintermediate) and address its direct role in experimental atherosclerosis by its adoptive transfer to hypercholesterolaemic apolipoprotein E deficient (apoE−/−) mice." (PMID 31823769, 2019).
atopic asthma (1 paper, 2021). An asthma that is characterized by symptoms that are triggered by an allergic reaction caused by inhaled allergens such as dust mite allergen, pet dander, pollen and mold. "The expression of IL-17RB and IL-17RA on eosinophils were found to be significantly higher in patients with atopic asthma." (PMID 34301307, 2021).